RNU7-9P (RNA, U7 small nuclear 9 pseudogene)
Synonyms: U7.9; LOC124906135
Gene: Small nuclear RNA gene on chromosome 2 (229,606,238 to 229,606,299, forward strand). Ensembl gene ENSG00000238782.
Homologues: Orthologues: chimpanzee U7 (98% identical), macaque U7 (97% identical). Paralogues in human: RNU7-2P (90% identical), RNU7-1 (89% identical), RNU7-26P (87% identical), RNU7-3P (87% identical), RNU7-10P (85% identical), RNU7-11P (85% identical), RNU7-12P (85% identical), RNU7-27P (85% identical), RNU7-41P (85% identical), RNU7-6P (85% identical), RNU7-7P (85% identical), RNU7-8P (85% identical), and 142 more.